SMAD3 (SMAD family member 3)
Diseases named in the same sentence as SMAD3 in open-access papers (continued):
Sharing a sentence is not in itself a finding about the gene and the disease.
type 2 diabetes (19 papers, 2015 to 2026). "By islet-specific RNA-seq, we revealed the unique Smad3-WT and Smad3-KO transcriptome profiles associated with type 2 diabetes development." (PMID 33456576, 2021). "Islet-specific RNA-sequencing was performed to identify Smad3-dependent differentially expressed genes associated with type 2 diabetes." (PMID 33456576, 2021). "By islet-specific RNA-sequencing, we identified 8160 Smad3-dependent differentially expressed genes associated with type 2 diabetes, where Smad3 deficiency markedly prevented the down-regulation of those genes." (PMID 33456576, 2021). "In this study, we discovered the pathogenic role of Smad3 in type 2 diabetes beta cell loss and dysfunction via the Pax6-dependent mechanism." (PMID 33456576, 2021). "There were 8106 Smad3-dependent differentially expressed genes associated with type 2 diabetes, where Smad3-KO largely decreased the number of down-regulated genes in db/db mice." (PMID 33456576, 2021). "Thus, transcriptional inhibition of the Pax6 in beta cells may represent as one of the key pathogenic mechanism for the Smad3-driven beta cell loss and dysfunction in type 2 diabetes." (PMID 33456576, 2021). "A recent study demonstrated that 8 weeks of aerobic exercise (30–50 min/day, six times/week for 8 weeks) improved renal interstitial fibrosis in type 2 diabetes (T2DM) mice by inhibiting the TGF-β1/Smad3 pathway through the upregulation of Sirt1 expression." (PMID 39796197, 2025). "The role of Smad3 in islet beta cell under type 2 diabetes condition was investigated by knocking out Smad3 in the db/db mice, which was described in our previous works 15-17." (PMID 33456576, 2021). "The chromatin states data certainly provided human evidence of the importance of Smad3 in human type 2 diabetes especially in islets." (PMID 33456576, 2021). "All these findings demonstrate an essential role for Smad3 in the pathogenesis of DN in both type 1 and type 2 diabetes." (PMID 34360646, 2021). "This was further demonstrated by the DIAMANTE T2D GWAS that the abundancy of active transcription start site was enriched on Smad3 gene, especially in pancreatic islets of type-2 diabetes patients compared to other tissues such as liver, adipose tissue, and skeletal muscle." (PMID 36147472, 2022). "Our findings strongly suggested that islet-specific silencing of Smad3 might represent as a novel therapeutic strategy for type 2 diabetes prevention and treatment." (PMID 33456576, 2021). "In addition, public ATAC-seq data also revealed a more active transcriptional regulatory potential of Smad3 in pancreatic islets of type 2 diabetes patients as compared with adipose tissue, liver and skeletal muscle." (PMID 33456576, 2021). "The huge differences in mouse serum insulin levels suggest that deletion of Smad3 may have an impact on islet beta cells in type 2 diabetes." (PMID 33456576, 2021). "Rationale: Transforming Growth Factor-beta (TGF-β) /Smad3 signaling has been shown to play important roles in fibrotic and inflammatory diseases, but its role in beta cell function and type 2 diabetes is unknown." (PMID 33456576, 2021). "Thus, results obtained from this and other studies reveal an essential role for Smad3 in the pathogenesis of type 2 diabetes and diabetic cardiorenal complications." (PMID 33733577, 2021). "We selected 14 disallowed genes for analysis based on their identification in 2 independent studies (C1qbp, Cd302, Cxcl12, Igfbp4, Ldha, Lmo4, Maf, Oat, Pdgfra, Slc16a1, and Smad3) and/or other criteria including up-regulation in type 2 diabetes (Acot7, Ldha, and Pdgfra)." (PMID 26038943, 2015). "However, the role of Smad3 in dyslipidemia and non-alcoholic fatty liver disease (NAFLD) in type 2 diabetes remains unclear, and whether targeting Smad3 has a therapeutic effect on these metabolic abnormalities remains unexplored." (PMID 37511155, 2023).
type 2 diabetes (continued). "Interestingly, we found the abundancy of active transcription start site and enhancer on Smad3 gene was especially increased in pancreatic islets of type 2 diabetes patients as compared to their liver, adipose tissue, and skeletal muscle according to the chromatin states data." (PMID 33456576, 2021). "Thus, our findings suggested Smad3 may represent as a novel therapeutic target for type 2 diabetes prevention and treatment." (PMID 33456576, 2021). "Thus, Smad3 may represent as a novel therapeutic target for type 2 diabetes prevention and treatment." (PMID 33456576, 2021). "Thus, islet-specific silencing of Smad3 may represent as a novel therapeutic strategy for the type 2 diabetes prevention and treatment." (PMID 33456576, 2021). "Therefore, better understanding of the TGF-β/Smad3 signaling in islet development may uncover new therapeutic strategy for type 2 diabetes." (PMID 33456576, 2021). "TGF-β/Smad3 signaling plays a critical role in type 2 diabetes (T2D) and type 2 diabetic nephropathy (T2DN), but treatment by specifically targeting Smad3 remains unexplored." (PMID 38164169, 2024).
Hyperglycemia (17 papers, 2013 to 2026). An increased concentration of glucose in the blood. "Smad3 activation under hyperglycemia disrupts cytoskeleton via transgelin and caspase-3, leading to podocyte damage." (PMID 41009556, 2025). "In DM rats with DKD, SG led to decrease of TGF-β1 and inhibited the activation of the TGF-β1/Smad3 signaling pathway by reversing the hyperglycemia." (PMID 38512446, 2024). "For example, increased CCGG methylation level in the upstream regulatory region of the Smad3 gene under hyperglycemia led to downregulation of the mRNA level of Smad3." (PMID 35544480, 2022). "We observed that suramin inhibited renal TGF-β1– mediated activation of SMAD-3 in the 9 and 17 week diabetic mice, supporting our previous finding of the anti-fibrotic potential of suramin in early hyperglycemia-induced kidney injury." (PMID 24040012, 2013). "According to a study regarding diabetic cardiomyopathy, miR-9 downregulation under hyperglycemia promoted fibroblast activation and collagen accumulation through TGF-β/Smad3 signaling." (PMID 41595522, 2026). "Under persistent hyperglycemia, TGF-β activation promotes Smad3 phosphorylation and nuclear translocation, thereby upregulating extracellular matrix proteins such as fibronectin (FN) and collagen IV (Col-IV)." (PMID 41487503, 2025). "We previously found that melatonin can alleviate hyperglycemia-induced renal inflammation by inhibiting the activation of TLR4 and the TGF-β1/Smad3 signaling pathway." (PMID 35979396, 2022). "Our results revealed that the expression levels of TGF-β, phosphorylated-Smad2 (p-Smad2) and phosphorylated-Smad3 (p-Smad3) were decreased with ENO1 knockdown, whereas the total Smad2 and Smad3 expression levels were not significantly different between the normal glucose and hyperglycemia groups." (PMID 31889896, 2019).
Sepsis (17 papers, 2015 to 2025). Sepsis is defined as life-threatening organ dysfunction caused by a dysregulated host response to infection. "USP11 inhibition by mitoxantrone ameliorated sepsis-associated AKI by downregulating TGFBR2/Smad3 signaling." (PMID 40656894, 2025). "On the other hand, inactivation of the TGF-β1/Smad3 pathway caused by curcumin was previously demonstrated to aid the alleviation of sepsis-induced acute lung injury in rat models." (PMID 35090386, 2022). "This in turn has been described in sepsis-induced myocardial dysfunction via Transforming Growth Factor β/Mothers against decapentaplegic homolog 3 (TGF-b/Smad3) signaling activation." (PMID 40253667, 2025). "In macrophages, we observed that the induction of pSmad3C was abrogated in Acvr1b-Lyz2cre mice, indicating that activin A is indeed indispensable for Smad3 activation in sepsis models induced by LPS and CLP surgery." (PMID 40067393, 2025). "The present study reveals that USP11 is a key regulator of sepsis-induced AKI through modulation of the TGFBR2/Smad3 pathway." (PMID 40656894, 2025). "Smad3 activation has been reported in muscle atrophy induced by a variety of conditions, including unloading, immobilization, denervation, sepsis, dystrophy, and aging." (PMID 40076640, 2025). "Our results showed that, in the SI‐AKI murine model, TGF‐β1/Smad3 signaling was activated upon sepsis‐induced kidney injury, resulting in increased expression levels of MMPs and TIMPs." (PMID 37525933, 2023). "This is particularly noteworthy as Smad3-related signaling pathways are widely-known to participate in the development of sepsis or intestinal injury." (PMID 35090386, 2022). "We determined that this activin A/Smad3 axis was a natural brake to inflammation, which prevented the overt activation of macrophages in response to inflammatory stimuli and suppressed inflammation in experimental sepsis and psoriasis." (PMID 40067393, 2025). "Overall, Smad3 activation by activin A suppresses the development of sepsis in mice." (PMID 40067393, 2025). "Recently, it had been reported that inhibition of the TGF-β1/Smad3 pathway might play a protective role in sepsis-induced acute lung injury." (PMID 33623823, 2021). "Furthermore, previous studies have reported that curcumin protects against sepsis-induced acute lung injury by inhibiting the expression of molecules involved in the TGF-β1/SMAD3 pathway." (PMID 25574201, 2015). "Similarly, a previous study has shown that curcumin pre-treatment could protect against sepsis-induced acute lung injury in a rat model by inhibiting the expression of the TGF-β1/Smad3 pathway." (PMID 29351226, 2018). "Importantly, this axis protects mice against the development of overt inflammation in models of sepsis, viral infection, and psoriasis, demonstrating a generalized mechanism, and suggesting that promoting the activin A/Smad3 pathway could provide a therapeutic strategy in these diseases." (PMID 40067393, 2025). "We also detected enhanced expressions of TGFBR2 and phosphorylated Smad3, indicating increased activation of the TGF-β/Smad signaling pathway in sepsis." (PMID 40656894, 2025). "Sepsis induces an immunosuppressive milieu, and previous studies indicate ZDHHC19's role in Smad3 palmitoylation, activating the TGF-β pathway." (PMID 38167131, 2024). "Thus, in the present study, we utilized the cecal ligation and perforation (CLP) murine model, a classic model of SI‐AKI, to assess whether the progression of sepsis‐induced renal injury is epigenetically regulated by PRMT1 through the TGF‐β1/Smad3 and IL‐6/STAT3 pathways." (PMID 37525933, 2023). "The work conducted by Cao showed that miR-145 inhibited LPS-induced inflammation and sepsis-induced lung injury via directly targeting TGF-β2 and inactivating TGFBR2/ Smad3 signaling both in septic patients and mice." (PMID 36012630, 2022).
Sepsis (continued). "We next investigated whether Smad3 could be phosphorylated in vivo during LPS-induced endotoxin shock and cecal ligation puncture–induced (CLP-induced) sepsis in mice." (PMID 40067393, 2025). "Furthermore, we analyzed the downstream TFs targeted by LR pairs and found that different TFs, including SMAD3, RBPJ, and MAX, were targeted in sepsis-only patients, while FOS, STAT3, STAT2, and RB1 were targeted in sepsis-induced patients." (PMID 35222683, 2022). "Interestingly, the expression of Inhba, Smad3, Acvr1b, Acvr2a, Stat5a, and Stat5b was all higher in the macrophages of patients compared with healthy volunteers, suggesting that the activin A/Smad3/STAT5 axis is also involved in human sepsis." (PMID 40067393, 2025).
acute kidney injury (16 papers, 2017 to 2026). Sudden and sustained deterioration of the kidney function characterized by decreased glomerular filtration rate, increased serum creatinine or oliguria. "In this article, the authors discover that severe acute respiratory syndrome coronavirus 2 (SARS‐CoV‐2) N protein can bind and activate Smad3 to induce kidney cell death and cause acute kidney injury (AKI) via p21‐dependent G1 cell cycle arrest mechanism." (PMID 34813685, 2022). "It was previously shown that the SARS-CoV-2 N protein is able to induce a Smad3-dependent cell cycle arrest in G1, via its interaction with Smad3, leading to acute kidney injury (AKI)." (PMID 38543494, 2024). "C-reactive protein interacts with Fcγ receptor II and activates Smad3 via ERK1/2/p38 to promote acute kidney injury." (PMID 31474876, 2019). "Gene deletion or drug inhibition of Smad3 blocks this pathway, and thereby improves acute kidney injury." (PMID 31474876, 2019). "Moreover, it has also been reported that the N protein induces apoptosis elevation and renal cells death in acute kidney injury though a Smad3-p21-dependent G1 cell cycle arrest mechanism leading to inhibition of tubular epithelial cells proliferation." (PMID 38355695, 2024). "Second, SARS-CoV-2 N protein can interact with Smad3 to form a complex to promote Smad3 signaling in response to TGF-β1and activate Smad3 to induce kidney cell death and cause acute kidney injury (AKI)." (PMID 37274117, 2023). "For the SARS-CoV-2 infection, its N protein interacts with Smad3 to activate TGF-β-Smad3 pathway and the downstream Smad3-dependent G1 cell cycle arrest for acute kidney injury." (PMID 41445958, 2025). "Smad3 (Mothers against decapentaplegic homolog 3) protein, a transcription factor/tumor suppressor in the transforming growth factor–beta (TGF-β) signaling, triggers the cell death pathway in acute kidney injury and induces a G1 cell cycle arrest in cells." (PMID 38543494, 2024).
coronary artery disease (16 papers, 2012 to 2025). "SMAD3 is a member of the TGFβ superfamily and has causal roles in aneurysm and coronary artery disease." (PMID 40931195, 2025). "We show here that TCF21 and JUN regulate expression of two presumptive causal coronary disease genes, SMAD3 and CDKN2B-AS1, in part by interactions with histone deacetylases and acetyltransferases." (PMID 31014396, 2019). "The genetic variants rs17465637 in MIA3, rs9818870 in MRAS, and rs17228212 in SMAD3 have been associated with coronary artery disease in GWA studies (P<5×10−8), although explaining only a small proportion of the coronary artery disease risk." (PMID 28737528, 2017). "Literature evidences point out strongly toward the importance of Smad3 protein in coronary heart diseases." (PMID 40465783, 2025). "In our study, we found four genes with single nucleotide variants (SNVs) associated with coronary artery disease—HNF1A, LOX, SMAD3, and SMARCA4, and one gene, EBF1, with a SNV associated with carotid intima media thickness for the gens in significant modules." (PMID 35925965, 2022). "SMAD3 is a transcriptional modulator activated by transforming growth factor β (TGF-β) and has been reported to be marginally associated with coronary artery disease, of which low HDL-C levels is a risk factor." (PMID 23468652, 2013).
idiopathic pulmonary fibrosis (16 papers, 2015 to 2025). Idiopathic pulmonary fibrosis (IPF) is a nonneoplastic pulmonary disease that is characterized by the formation of scar tissue within the lungs in the absence of any known cause. "In a study, paracrine signaling from fibroblasts derived from patients with idiopathic pulmonary fibrosis was shown to activate the IL-6/STAT3 and TGF-β/Smad3 pathways in healthy lung fibroblasts, contributing to fibrotic progression." (PMID 40806851, 2025).
thoracic aortic aneurysm (16 papers, 2012 to 2025). An aneurysm formed in the wall of the proximal portion of the descending aorta proceeding from the arch of the aorta. "The patient in whom this SMAD3 variant was first identified has developed both a thoracic aortic aneurysm as well as an abdominal aortic aneurysm." (PMID 36926042, 2023). "In a previous study, targeted NGS revealed 1 novel splice‐site variant, c.871+1G>A in SMAD3, in two patients with nonsyndromic familial thoracic aortic aneurysms/dissections." (PMID 37183561, 2023). "SMAD3, the second most connected hub node, plays an important role in cardiogenesis, and is linked to thoracic aortic aneurysm and dissection." (PMID 35463757, 2022). "According to several studies, the SMAD family is related to the formation of thoracic aortic aneurysm, and animal experiments have proven that the deficiency of SMAD3 would promote the formation of thoracic aortic aneurysm." (PMID 34093163, 2021). "Previous studies have shown SMAD3 gene mutations to be associated with thoracic aortic aneurysms, abdominal aortic aneurysms and to a predisposition to ICAs." (PMID 32597575, 2020). "Pathogenic SMAD3 variants are responsible for a cardiovascular phenotype, mainly thoracic aortic aneurysms and dissections." (PMID 32154675, 2020). "Pathogenic SMAD3 variants are responsible for a cardiovascular phenotype, mainly thoracic aortic aneurysms and dissections, with variable expressivity and incomplete penetrance." (PMID 32154675, 2020). "In this study we report two apparently unrelated Cypriot families with nonsyndromic familial thoracic aortic aneurysm and dissection associated with a novel variant in SMAD3." (PMID 32597575, 2020). "Nonetheless, haploinsufficiency of other TGFβ signaling components, such as the SMAD3 effector and the TGFβ2 ligand, which also leads to pathologically increased TGFβ signaling has previously been suggested as the disease mechanism causing thoracic aortic aneurysms and various associated features." (PMID 24587008, 2014). "Defects in genes, including TGFB2, TGFBR2, TGFBR1 and SMAD3, are responsible for 10% of familial nonsyndromic thoracic aortic aneurysms/dissections." (PMID 37183561, 2023). "Indeed, pathogenic variants or deficiency of TGF-β pathway genes, including TGFB2, TGFB3, TGFBR1, TGFBR2, and SMAD3, confer risks for aortic destruction and thoracic aortic aneurysm formation." (PMID 38916960, 2024).